AGL (amylo-alpha-1,6-glucosidase and 4-alpha-glucanotransferase)
Description:
Multifunctional enzyme acting as 1,4-alpha-D-glucan:1,4-alpha-D-glucan 4-alpha-D-glycosyltransferase and amylo-1,6-glucosidase in glycogen degradation.
Synonyms: GDE
Tractability: Antibody: its Gene Ontology location is reachable by antibodies, with high confidence. PROTAC: UniProt records ubiquitination sites on it; ubiquitination databases record sites on it; its protein half-life has been measured; a small molecule that binds it is known.
Target class: Enzyme
Gene: Protein-coding gene on chromosome 1 (99,849,777 to 99,924,024, forward strand). Ensembl gene ENSG00000162688.
Subcellular location: Cytoplasm
Subcellular location (Human Protein Atlas): Nucleoplasm; Cytosol; Nuclear bodies
Pathways (Reactome):
Immune System: Neutrophil degranulation
Metabolism: Glycogen breakdown (glycogenolysis)
Gene Ontology:
Molecular function: 4-alpha-glucanotransferase activity; amylo-alpha-1,6-glucosidase activity; protein binding; carbohydrate binding; polysaccharide binding; polyubiquitin modification-dependent protein binding
Biological process: glycogen catabolic process; carbohydrate metabolic process; glycogen biosynthetic process; response to glucocorticoid; response to hormone; response to nutrient
Cellular component: cytoplasm; cytosol; nuclear body; nucleoplasm; extracellular region; ficolin-1-rich granule lumen; isoamylase complex; secretory granule lumen; inclusion body; nucleus; sarcoplasmic reticulum
Genetic constraint (gnomAD): Loss-of-function variants: 119 observed, 192.52 expected, observed/expected ratio (o/e) 0.62, 90% interval 0.53 to 0.72. The upper end of that interval is the gene's LOEUF score, 0.72, which puts it in group 2 of 6, group 1 being the genes least tolerant of losing a copy. Missense variants: 1,744 observed, 1,847.2 expected, observed/expected ratio (o/e) 0.94, 90% interval 0.91 to 0.98. Synonymous variants: 564 observed, 608.69 expected, observed/expected ratio (o/e) 0.93, 90% interval 0.86 to 0.99.
Gene-disease validity (ClinGen):
ClinGen rates the evidence that AGL causes each of these diseases.
glycogen storage disease III (autosomal recessive): Definitive. Glycogen debranching enzyme (GDE) deficiency, or glycogen storage disease type 3 (GSD 3), is a form of glycogen storage disease characterized by severe muscle weakness and hepatopathy.
Homologues: Orthologues: chimpanzee AGL (99% identical), macaque AGL (98% identical), dog AGL (94% identical), rabbit AGL (93% identical), pig AGL (93% identical), guinea pig AGL (93% identical), rat Agl (92% identical), mouse Agl (92% identical), tropical clawed frog agl (78% identical), zebrafish agla (75% identical), zebrafish aglb (47% identical), Drosophila melanogaster CG9485 (47% identical), and 1 more.
Diseases named in the same sentence as AGL in open-access papers:
AGL is named in the same sentence as 51 diseases in open-access papers, as found by Europe PMC text mining. Sharing a sentence is not in itself a finding about the gene and the disease. The quoted sentences say what the papers report.
Glycogen storage disease type III (30 papers, 2009 to 2026). "AGL gene causing glycogen storage disease IIIa/IIIb (GSD3a/3b) was the most common gene affecting this group (19 children/14 variants)." (PMID 41165782, 2025). "Mutations in AGL have been associated with glycogen storage disease type III in different ethnicities." (PMID 39858027, 2025). "Variants in AGL (Glycogen storage disease type-III; GSD3), ABCB4 (Progressive familial intrahepatic cholestasis type-III; PFIC3) and ABCB11 (PFIC2) genes were the most common affecting 19, 14 and 13 children, respectively." (PMID 41165782, 2025). "A total of 1 high‐risk parent with the same pathogenic gene AGL (glycogen storage disease type III) was detected among the 78 parents, with the detection rate of 0.3%." (PMID 38562051, 2024). "Mutations in AGL are associated with glycogen storage disease IIIa and IIIb, which lead to amylo-1,6-glucosidase deficiency, hypoglycemia, hyperlipidemia, elevated transaminases, and increased serum creatine kinase, but normal blood lactate and uric acid." (PMID 38592052, 2024). "Glycogen storage disease Type III (GSD III) (#MIM 232400) is an autosomal recessive disease due to deficiency of the debranching enzyme (GDE) encoded by the AGL gene, located on chromosome 1p21." (PMID 37252245, 2023). "Glycogen storage disease type III (GSDIII) is caused by mutations of AGL gene with debranching enzyme deficiency." (PMID 30916492, 2019). "Glycogen Storage Disease Type III (GSD III) is a rare autosomal recessive metabolic disorder caused by AGL gene mutation." (PMID 29614965, 2018). "Loss of AGL is known to cause Glycogen Storage Disease III (GSDIII) which results in accumulation of abnormally branched glycogen predominantly in liver and skeletal muscle." (PMID 29682180, 2018). "Finally, a recent report described a case of paternal UPD resulting in homozygous mutations in both USH2A and AGL (glycogen storage disease type III) genes in a 4-year-old girl with congenital deafness, learning difficulties, and enlarged liver." (PMID 36051698, 2022). "Likewise, mutations in AGL gene (Cori disease, GSD III) provoke amylo-1,6-glucosidase deficiency and abnormalities in glycogen metabolism." (PMID 33673114, 2021). "Glycogen storage disease type III (GSDIII) is a rare inborn error of metabolism, with an incidence of 1 in 100,000, caused by mutations in the AGL gene, which encodes for the glycogen debranching enzyme (GDE; also known as amylo-α-1,6-glucosidase)." (PMID 38015640, 2024). "Glycogen storage disease type III (GSDIII) is a rare, autosomal recessive disorder with an incidence of 1 in 100,000 live births due to mutations in the amylo-α-1, 6-glucosidase, 4-α-glucanotransferase (AGL) gene." (PMID 38753465, 2024). "Among them, glycogen storage disease type III (GSDIII; incidence: 1/100,000) is caused by mutations in the AGL gene encoding the glycogen debranching enzyme (GDE) which catalyzes the degradation of glycogen." (PMID 37250895, 2023). "Glycogen storage disease type III (GSDIII) is a uncommon autosomal recessive inherited metabolic disorder, which is caused by variants in the AGL gene." (PMID 37287601, 2023). "Glycogen storage disease type III (GSDIII, MIM #232400) is an autosomal recessive disorder caused by a deficiency of glycogen debranching enzyme (GDE, EC 3.2.1.33, EC 2.4.1.25) encoded by AGL (MIM #610860)." (PMID 33728245, 2021). "Glycogen storage disease type III is caused by mutations in the AGL gene (OMIM 610860) that encodes a glycogen debranching enzyme that possesses two catalytic activities, namely, amylo-1,6-glucosidase, and 4-alpha-glucanotransferase." (PMID 33329388, 2020). "Inactivation of AGL leads to buildup of abnormal glycogen in the liver, heart and skeletal muscle leading to Glycogen Storage Disease III (GSD III), a condition with good prognosis when treated by high protein and complex carbohydrate diet." (PMID 27595989, 2016).
Glycogen storage disease type III (continued). "In humans, mutations in the glycogen debranching enzyme (AGL) and the muscle isoform of PFK cause or Glycogen Storage Disease type III and Glycogen storage disease type VII, respectively." (PMID 25692684, 2015). "Glycogen storage disease type III (GSDIII) is a rare inborn error of metabolism affecting liver, skeletal muscle, and heart due to mutations of the AGL gene encoding for the glycogen debranching enzyme (GDE)." (PMID 38015640, 2024). "GSD type III, also known as Cori or Forbes disease, is caused by mutations in the AGL gene, which results in glycogen debranching enzyme deficiency, an enzyme that helps facilitate the breakdown of glycogen and mobilize glucose reserves from glycogen deposits in the muscles and liver." (PMID 37601653, 2023). "Glycogen storage disease type III (GSDIII) is an autosomal recessive inherited metabolic disease, which is caused by variants in the AGL gene leading to a deficiency in glycogen debranching enzyme (GDE) during the glycogen degradation pathway." (PMID 37287601, 2023).
glycogen storage disease (16 papers, 2020 to 2025). "Loss of AGL is classically associated with glycogen storage disease and has also been found to be associated with bladder cancer and proliferation of bladder cancer cells, although none of the patients in the current study had bladder cancer." (PMID 39184053, 2024). "Glycogen storage disease (GSD) Type IIIa is an autosomal recessive disorder caused by bi‐allelic mutations in the AGL gene on chromosome 1p21, resulting in an impaired glycogen debranching enzyme." (PMID 35433175, 2022). "GSDIII caused by a deficiency in glycogen debranching enzyme (GDE) encoded by the AGL gene that is which located on chromosome 1p21, is the second most frequent cause of glycogenosis." (PMID 33344388, 2020). "These included recurrent disease-causing variants for glycogen storage disease IIIa/IIIb (AGL), progressive familial intrahepatic cholestasis type 1 (ATP8B1), and Niemann–Pick disease type A/B (SMPD1)." (PMID 33083013, 2020). "Glycogen storage disease (GSD) type III (OMIM 232400) is an autosomal recessive inherited error of metabolism caused by the deficiency of glycogen debranching enzyme amylo-1,6-glucosidase, encoded by AGL gene, resulting in an incomplete glycogen degradation and its accumulation." (PMID 32714838, 2020). "Complete or partial deficiency or mutation of AGL leads to autosomal recessive glycogen metabolism disorders, known as Type III glycogen storage disease." (PMID 40941421, 2025). "Cori–Forbes disease [OMIM:232400] is an AR glycogen storage disorder (type III) caused by homozygous or compound heterozygous mutations affecting the amylo-α-1,6-glucosidase/4-α-glucanotransferase (AGL) gene located on chromosome 1p21." (PMID 37239976, 2023). "This study reported 12 Chinese patients with Glycogen storage disease and identified 18 gene variants of GAA, AGL, PHKA2 and PYGL (9 novel and 9 reported) by whole-exome sequencing." (PMID 36105079, 2022). "Inactivation of AGL participated in the pathogenesis of glycogen storage disease." (PMID 33391344, 2020). "Notably, 2/8 proteins that regulate the lysosomal storage disorder glycogen storage disease were highlighted in the EL network of AF and 2 more (PYGB and AGL) were significantly upregulated in TL." (PMID 38827406, 2024).
bladder cancer (9 papers, 2016 to 2025). "Bladder cancer cells with deficient AGL expression have a higher glycolytic activity and glycine synthesis capacity than those with normal expression of AGL, and this capacity can greatly contribute to the proliferation of bladder cancer." (PMID 34136492, 2021). "We have shown that loss of AGL results in aggressive anchorage dependent and independent growth of bladder cancer cells." (PMID 29682180, 2018). "It has been clearly shown by us here and in bladder cancer that loss of AGL's enzymatic activity or inhibition of glycogen breakdown does not positively impact tumor growth." (PMID 29682180, 2018). "Anchorage dependent and independent proliferation assay showed that loss of both CD44 and RHAMM inhibited growth of bladder cancer cells driven by AGL loss." (PMID 27595989, 2016). "This revealed that bladder cancer cells whose aggressive growth is mediated by loss of AGL are susceptible to apoptosis with loss of HAS2, CD44 or RHAMM." (PMID 27595989, 2016). "TUNEL staining showed more apoptotic cells with loss of HAS2, CD44 or RHAMM in AGL low bladder cancer cells." (PMID 27595989, 2016). "We have earlier shown that loss of AGL induces rapid growth of bladder cancer cells via HAS2 mediated HA synthesis." (PMID 27595989, 2016). "Detailed investigation is required to understand how death receptor signaling and apoptosis is triggered by either CD44 or RHAMM knockdown in rapid growing bladder cancer cells driven by AGL loss." (PMID 27595989, 2016). "Our previous study and current research have looked in detail into the involvement of HA signaling for aggressive growth of bladder cancer cells driven by AGL loss." (PMID 27595989, 2016). "Here we explore the role of CD44 and RHAMM in the rapid growth of bladder cancer cells mediated by AGL loss." (PMID 27595989, 2016). "4MU, a well-known inhibitor of HA synthesis, has been shown by us to inhibit HA synthesis and growth of bladder cancer cells driven by loss of AGL." (PMID 27595989, 2016). "We have established that loss of AGL promotes rapid bladder cancer growth via HAS2-HA-CD44/RHAMM pathway." (PMID 27595989, 2016). "LMW HA at 100 μg/ml partially rescued the growth inhibition caused by 4MU treatment of AGL knockdown bladder cancer cells." (PMID 27595989, 2016). "This also provides evidence that CD44 and RHAMM are involved in HAS2/HA signaling in bladder cancer cells with loss of AGL." (PMID 27595989, 2016). "Recently, the glycogen debranching enzyme AGL was shown to have tumour suppressor function in bladder cancer, and that loss of AGL leads to increased tumour growth in xenograft models of bladder cancer." (PMID 26882899, 2016). "Through metabolomics and transcriptomic analysis we identified that loss of AGL makes bladder cancer cells dependent on Serine Hydroxymethyltransferase 2 (SHMT2) driven glycine synthesis and Hyaluronic Acid (HA) Synthase 2 (HAS2) driven HA synthesis for aggressive growth." (PMID 29682180, 2018). "MGHU4 bladder cancer cells, with loss of AGL, have shown rapid growth driven by the HAS2/HA axis." (PMID 27595989, 2016). "Loss of AGL promotes anchorage dependent and independent growth of bladder cancer cells." (PMID 27595989, 2016). "Change is cellular location of RHAMM with AGL loss in some bladder cancer cell lines (UMUC3) could be a determining factor on how this protein functions." (PMID 27595989, 2016). "We observed something similar in rapid growing bladder cancer cells driven by AGL loss." (PMID 27595989, 2016). "Thus showing that loss of RHAMM is a major inducer of apoptotic signaling in bladder cancer cells driven by AGL loss." (PMID 27595989, 2016). "Moreover knockdown of HAS2, CD44 and RHAMM reduced growth and induced apoptosis predominantly in the AGL knockdown bladder cancer cells confirming that loss of AGL drives bladder cancer growth via HAS2/HA/CD44-RHAMM axis." (PMID 27595989, 2016).
bladder cancer (continued). "Our findings strongly point to the importance of the HAS2-HA-CD44/RHAMM pathway for rapid growth of bladder cancer cells with loss of AGL and provides rational for targeting this pathway at various steps for “personalized” treatment of bladder cancer patients based of their AGL expression status." (PMID 27595989, 2016). "AGL, primarily known for its role in glycogen breakdown, has been identified as a significant factor in bladder cancer." (PMID 38256214, 2024). "AGL was primarily responsible for breaking down glycogen and was suggested to be closely connected with bladder cancer." (PMID 33991070, 2021). "These experiments suggest that AGL low rapid growing bladder cancer cells are vulnerable to apoptosis on inhibition of HA synthesis." (PMID 27595989, 2016). "We have identified AGL as a tumor growth suppressor and prognostic marker in human bladder cancer, for the first time showing AGL plays a role in cancer biology." (PMID 27595989, 2016). "This would point to new therapeutic avenue for bladder cancer patients based of their AGL expression levels." (PMID 27595989, 2016). "Bladder cancer cells with low AGL expression were found to be more sensitive to glucose deprivation and glycolysis inhibition by 2-deoxygl-D-glucose." (PMID 26882899, 2016). "These outcomes illustrate that specific AGL knockdown bladder cancer cell lines undergo apoptosis with inhibition of either CD44 or RHAMM and loss of this particular HA receptor also inhibit HA synthesis by a feedback mechanism." (PMID 27595989, 2016). "Here we focus on the importance of CD44 and RHAMM in driving the rapid growth of bladder cancer cells with low AGL expression." (PMID 27595989, 2016). "We also identified that RHAMM mRNA expression alone and in combination with AGL mRNA expression serves as a prognostic marker in bladder cancer." (PMID 27595989, 2016). "We observed loss of either CD44 or RHAMM is important for induction of apoptosis in specific AGL low bladder cancer cell line." (PMID 27595989, 2016). "The mechanism how CD44 and RHAMM drives growth of bladder cancer cells that have lost AGL will be investigated in future." (PMID 27595989, 2016). "CD44 and RHAMM both play a role in inhibiting anchorage dependent and independent growth of bladder cancer cells with low AGL expression." (PMID 27595989, 2016). "Here we aim to study the role of CD44 and RHAMM, downstream of HA, in rapid growth of bladder cancer cells driven by low AGL expression." (PMID 27595989, 2016). "Growth assays showed that loss of CD44 and RHAMM predominantly inhibit anchorage dependent and independent growth of AGL low bladder cancer cells." (PMID 27595989, 2016). "We propose that bladder cancer patients with low AGL expression are an ideal subset of cancer patients who can be treated with CD44 and RHAMM inhibitors." (PMID 27595989, 2016). "These bladder cancer cells transduced with control shRNA (shCTL) and shRNA against AGL (shAGL) has been used by us in previous research projects." (PMID 27595989, 2016). "Another study found that hyaluronic acid 2 (HAS2) is the driver of tumour growth of bladder cancer with low AGL, suggesting a preclinical rational for personalised targeting in patients with low AGL expressing bladder tumours." (PMID 26882899, 2016). "Since high RHAMM expression is a predictor of poor outcome in bladder cancer patients, we examined the utility of combining AGL and RHAMM expression in stratifying bladder patient outcome." (PMID 27595989, 2016). "Here we study the role of HA’s two main receptors in bladder cancer growth driven by low AGL expression." (PMID 27595989, 2016). "Loss of Amylo-alpha-1-6-glucosidase-4-alpha-glucanotransferase (AGL) drives rapid proliferation of bladder cancer cells by upregulating Hyaluronic acid(HA) Synthase (HAS2) mediated HA synthesis." (PMID 27595989, 2016). "AGL was regarded as a biomarker that suppressed tumor growth in bladder cancer." (PMID 33991070, 2021).